MIR6751 (microRNA 6751)
Synonyms: hsa-mir-6751
Gene: MicroRNA gene on chromosome 11 (65,129,916 to 65,129,978, reverse strand). Ensembl gene ENSG00000284489.
Homologues: Orthologues: chimpanzee MIR6751 (100% identical).